CD4 (CD4 molecule)
Diseases named in the same sentence as CD4 in open-access papers (continued):
Sharing a sentence is not in itself a finding about the gene and the disease.
infection (continued). "However, the early phase of illness and wasting (occurring after the first few days of intravenous infection) is independent of CD4+ T-cell function in this same model." (PMID 27435819, 2016). "Anti-Tat IgM were preferentially detected in chronic HIV-infected subjects with low T cell activation (p-value = 0.03) and correlated with higher CD4+ T cell counts and lower viral loads irrespective of the duration of infection (p-value = 0.019 and p-value = 0.037 respectively)." (PMID 27450538, 2016). "We compared HIV-1 integration sites patterns between macrophages and CD4+ T cells derived from seven ART-treated HIV-1-infected individuals whose cells were infected ex vivo with autologous, as well as heterologous, primary HIV-1 isolates generated during the acute phase of infection." (PMID 27067385, 2016). "Infection of CCL19-treated resting CD4+ T cells with mutant strains of HIV, lacking NF-κB binding sites in the HIV long terminal repeat (LTR) compared to infection with wild type virus, led to a significant reduction in integration by up to 40-fold (range 1–115.4, p = 0.03)." (PMID 27459960, 2016). "Furthermore, there was an increased in the frequency of CD45RA+ cells at 7 days post infection compared to prior to infection in CD38+ but not in CD38- CD4+ T cells." (PMID 27662621, 2016). "We have resolved how CD4+ IFN-γ+ IL-10+ T cells distribute systemically within nonlymphoid tissues during infection to limit inflammation, and we have identified pathways that orchestrate IL-10 production by effector CD4+ IFN-γ+ T cells, potentially at distinct phases of infection." (PMID 26459508, 2016). "We found that the proportion of CD45RA+ within CD38+ but not CD38- CD4+ T cells is significantly increased upon infection and CD38 has been shown to be preferentially expressed by CD45RA+ CD4+ T cells and might play a role for lymphocyte homing on those cells." (PMID 27662621, 2016). "However, CD4+IFN-γ–yellow fluorescent protein (YFP)+IL-10–GFP− memory T cells rapidly express IL-10 during parasite re-exposure, which leads to enhanced IL-10 production during secondary malaria infection compared with primary infection." (PMID 27630165, 2016). "Nonetheless, homing to the CNS by CD4+ cells was reduced, arguing that the absence of miR-155 may affect the ability of these cells to efficiently migrate to sites of infection." (PMID 27604627, 2016). "However, none of the data presented indicates that non-mac-tropic Envs consistently mediate more efficient infection of CD4+ T-cells compared to mac-tropic Envs." (PMID 25809903, 2015). "Interestingly, GATA-3-expressing CD4+ T cells, which are considered Th2-type T cells, accumulated more quickly and to higher levels than T-bet-expressing CD4+ T cells, regardless of the Mtb strain, and the levels peaked at 28 days post-infection." (PMID 26675186, 2015). "Interestingly, Jønsson and coworkers reported that romidepsin was able to prevent the de novo infection of PBMCs and CD4+ T cells but not in MDMs in vitro and reminded that a complete eradication is only possible by considering all latent reservoirs together." (PMID 26405463, 2015). "Thus coimmunization of sFliC and STm alters the IFN‐γ response to STm and the IL‐4 response to sFliC in both transgenic and endogenous CD4 T cells without altering the capacity of mice to control the early stages infection." (PMID 26036767, 2015). "Early during infection, TGF-β signaling suppressed the expression of the high affinity IL-2 receptor α chain (CD25) on virus-specific CD4 T cells, which tempered IL-2 signaling and STAT5 and mammalian target of rapamycin (mTOR) activation in Tfh precursor CD4 T cells." (PMID 25569154, 2015). "While this might have been the case in STAT-6−/− animals in which numbers of IFN-γ+ CD4 cells substantially increased following infection with the mutant virus, it did not hold true for the IL-13−/− mice." (PMID 25751266, 2015).
infection (continued). "Infection did not result in increased IL-10 production by CD4− cells (data not shown)." (PMID 26195548, 2015). "We were unable to define subtype related differences in viral load or CD4 count but have to acknowledge that it is a shortcoming of this study that viral load and CD4 data were based on single measurement and could not be corrected for time of infection." (PMID 26572861, 2015). "Intriguingly CD4+ and CD8+ T cells showed a significant increase of EGFR expression in the METH exposed LCMV infected group than LCMV alone by 56 days post infection, while a trend of increased expression in the METH treated group was observed at all time-points analyzed." (PMID 26322025, 2015). "Liman and Rautenschlein demonstrated that the percentage of CD4+ T cells subpopulation (but not CD8+ T cells) increased briefly in HG of turkeys 7–14 DPV after vaccination with aMPV/B or after infection with aMPV/A or B, which corroborates our results for MDA+ vaccinated birds." (PMID 25889279, 2015). "Finally, the finding that double infection did not occur stochastically across all subsets but rather was favored in central memory (TCM) cells further confirms the heterogeneity of CD4+ T cells with respect to HIV infection." (PMID 26559763, 2015). "Moreover, formation of CD4+ follicular helper (TFH)/B cell conjugates is crucial for B cell differentiation and class switch recombination to generate high-affinity antibodies for host protection following infection with L. major parasites." (PMID 26557117, 2015). "However, the induction of productive infection does not inevitably lead to post-integration latency in resting CD4+ T-cells, as observed following co-culture with CD14loCD16hi monocytes, B-cells and pDC." (PMID 26362311, 2015). "In addition, the results indicate that the absence of NK, NKT and CD8 T cells, but not CD4 T cells, during the early stage of infection results in a reduced anemic phenotype similar to IFNγR-/- mice." (PMID 26070118, 2015). "However, the relationship between infection in the lung parenchyma and decreased CD4+ T cells in BAL has not been determined." (PMID 25933119, 2015). "Our data show that non-mac-tropic R5 Envs either from early or late disease do not mediate more efficient infection of CD4+ T-cells compared to mac-tropic Envs, even though they are likely to predominantly target T-cells and dominate over more mac-tropic variants in immune tissue in vivo." (PMID 25809903, 2015). "However, in C57BL/6 mice lacking B or CD4 T lymphocytes, ECTV causes a persistent infection and chronic stimulation of CTL activity." (PMID 26700306, 2015). "Thus, following CD4+ T cell, CD8+ T cell or mock depletion during and for 5 weeks post MusPV1 challenge, all mice were then switched to anti-CD3 antibody administration for a further 10 weeks to allow for re-activation of any persistent MusPV1 infection." (PMID 26495972, 2015). "The ability to prevent a biologically heterologous, CD4-independent/CCR5+ viral isolate and the macrophage-tropic SIVmac316 strain from establishing infection supports the hypothesis that direct target cell blocking is unlikely to be a central feature of live lentivirus vaccination." (PMID 25834093, 2015). "Latently infected cells were defined as nonproliferating CD4+ T cells not expressing viral-encoded GFP and were thus sorted by fluorescence-activated cell sorting (FACS) as SNARF-1high and GFP− cells after 5 days post-infection." (PMID 25586146, 2015). "Thus, in the absence of a productive infection of murine CD4 T cells, HIV-GFP becomes opsonized in vivo and is transported to the FDC within the follicles of the draining LNs." (PMID 26623655, 2015). "In section 3.6, the initial phase of infection of both SRLVs and HIV-1 targets monocyte/macrophage cell lineages but, unlike SRLVs, HIV-1 also infects the CCR5+ CD4+ T cells where it mainly replicates in the gut-associated lymphoid tissues (GALT) early post-infection." (PMID 29061947, 2015).
infection (continued). "Furthermore, numbers of actively proliferating (Ki-67+) CD8+CD44hi dextramer-negative and CD4+ cells were comparable in WT and rpS6P−/− mice, suggesting that the overall T cell response to Lm-Ova infection was similar in both groups." (PMID 26453749, 2015). "In order to determine whether appropriate memory responses were generated in the VLP-treated CD4+, CD8+, IFN-gamma, or TNF alpha knockout (or antibody depleted) mice that survived infection, these mice were re-challenged with EBOV >28 days later, without additional VLP treatment." (PMID 25785602, 2015). "Here, we investigated whether Env+ pseudoviruses bearing transmitted/founder (T/F), early and late disease non-mac-tropic R5 envelopes mediated more efficient infection of CD4+ T-cells compared to those with highly mac-tropic Envs." (PMID 25809903, 2015). "Furthermore, tTreg contributed proportionally less IL-10 relative to other CD4+ cell types in 4x skin, and their number was not significantly different between the two infection groups." (PMID 25974019, 2015). "However, after repeated infections (i.e., 4×), CD4+ cells were not able to proliferate or secrete cytokines in response to antigen restimulation." (PMID 25624353, 2015). "The recipients transferred with 1 × 107 CD4+ T cells could control the challenge infection, but those with 1 × 106 CD4+ T cells could not." (PMID 25760084, 2015). "Within CD4+ T cells, double-cytokine-producing cells were virtually absent prior to infection, but could be identified from week 2 after primary infection onwards." (PMID 25971313, 2015). "However, this is unlikely because infection did not increase the expression of FasL on CD4+ T cells, in contrast to CD8+ T cells." (PMID 25760084, 2015). "It is reasonable to propose that periluminal CD4+ cells, with or without the help of gp340 or other alternative binding molecules, could bind the virus, and become targets of infection in the presence of CCR5." (PMID 26172445, 2015). "We tested whether the T/F, acute and late non-mac-tropic R5 Envs have an increased ability to confer infection of CD4+ T-cells compared to highly mac-tropic R5 Envs." (PMID 25809903, 2015). "Despite not being infected, FDCs are a source of infection for CD4 T cells." (PMID 26623655, 2015). "Notably on days 4 and 7 p.i. the recruitment of macrophages, total lymphocytes, T-cells, and CD4+ and CD8+ T-cells was increased following infection with vΔ169 compared to controls, and these differences may explain the more rapid clearance of this virus." (PMID 26334635, 2015). "However, in BLT mice, the growth of HIV-1 fsΔ-1 and HIV-1 fsΔ-13 was ~3-fold lower than WT HIV-1, and the level of systemic CD4+ T cell decrease and thymopathy by HIV-1 fsΔ-1 and HIV-1 fsΔ-13 infections (~50% reduction) were milder than WT HIV-1 (~90% reduction)." (PMID 25807049, 2015). "Information of this kind has so far been lacking for IE-1-specific CD4 T cells, but identification of their target epitopes makes it now possible to undertake precise analyses of their role in combating infection and disease and to explore their function in adoptive T-cell therapy." (PMID 26635812, 2015). "Both mac-tropic and non-mac-tropic R5 Envs conferred infection of CD4+ T-cells." (PMID 25809903, 2015). "In the absence of any effective Cryptococcus-specific CD4 response, microglial cells and CNS macrophages are unable to effectively restrict cryptococcal growth, leading to high organism burdens, poor clearance of infection during treatment, and high mortality." (PMID 25853653, 2015). "It is therefore possible that the type I IFN response induced by HIV infection is protective against C. neoformans only until CD4 T cells fall below a critical threshold after which the protective effects are lost and the lack of CD4 T cells results in uncontrolled infection." (PMID 26252005, 2015).
infection (continued). "Thus, our data identify IL-27 signaling as a novel pathway to prevent the early mortality via inhibiting hyperactivation of CD4+ Th1 cells and their excessive secretions of IFN-γ during experimental infection with extracellular protozoan parasites African trypanosomes." (PMID 26222157, 2015). "However, comparing these responses in infection models that generate overall weak CD4 T cell responses due to poor activation does not allow accurate comparison of the capacity of the non-cognate CD4 T cell response." (PMID 25540644, 2014). "However, after infection there was a significant reduction in the number, but not the percentage, of CD4+ T cells in MLN of mice developmentally exposed to TCDD." (PMID 25051576, 2014). "Using anti-Leu3a, a monoclonal antibody recognizing CD4, HIV-positive patients have been found to express CD4 molecule at the surface of parathyroid gland cells, indicating the possibility of either functional inhibition by anti-CD4 antibodies or direct infection by HIV." (PMID 24587936, 2014). "In addition, group 4 patients with severe infection were more accurately identified by determination of HCMV-specific rather than total CD4+ T-cells (area under the ROC curve at 60 days after transplantation: 0.90 vs 0.84)." (PMID 25166270, 2014). "In response to TMEV infection, CD4+ and CD8+ T cells are primed in the periphery, which subsequently infiltrate into the CNS and mount antiviral immune responses, leading to effective viral clearance within the first weeks of infection in resistant C57BL/6 mice." (PMID 25391297, 2014). "Importantly, we also found that in vitro infection of CXCR5-expressing CD4 T cells did not impact CXCR5 surface expression." (PMID 24497824, 2014). "Thus, to determine whether Treg depletion after infection influences bacterial burden, we made use of DEREG mice that allow the specific depletion of FoxP3+CD4+ Tregs cells by administering DT." (PMID 25050936, 2014). "In order to assess the nature of the T cells recruited to the site of infection, FP granuloma lymphocyte populations from each strain were stimulated with various M. leprae crude and purified antigens in vitro and evaluated by flow cytometry for IFN-γ production by CD4+CD44+ and CD8+CD44+ cells." (PMID 25210773, 2014). "While IFN-γ-producing Th1 cells do play a role in controlling acute infections, and they contribute to acute erythrocytic-stage pathology, it became apparent that a classical Th2 response producing IL-4 is not a critical feature of the CD4+ T-cell response during the chronic phase of infection." (PMID 25628621, 2014). "Virus-specific IL-17-producing CD4+ T cells have also been detected in mice following herpes simplex virus (HSV), Theiler's murine encephalomyelitis virus (TEMV), and vaccinia virus (VV) infection, among others, albeit at a lower magnitude than the prototypical antiviral TH1 response." (PMID 24586147, 2014). "Furthermore, the lack of the P2X7R during MP287/03 Mbv infection did not affect the low production of IL-1β by lung infiltrating cells, but it restored the CD4+ and CD8+ T cell responses with the secretion of more IFNγ and less IL-10." (PMID 24991816, 2014). "Indeed, while CAR expression was almost equal within the CD4+ and CD8+ T cell populations immediately after infection, the antigenic restimulation determined the progressive accumulation of the CD8+ T cell subset only, which almost completely overcame CD4+ T cells by month one after transduction." (PMID 25279468, 2014). "However, while CD4+Foxp3+ Tregs that were adoptively transferred 2 days prior to JEV infection made the recipients vulnerable to JE, CD4+Foxp3+ Tregs that were adoptively transferred 2 days after infection provided resistance to JE (unpublished personal data)." (PMID 25188232, 2014). "CD4 was efficiently down-modulated by the virus, as expected, whether the cells were activated or not after infection." (PMID 25330112, 2014).
infection (continued). "Further studies are needed to define the signals necessary for the local differentiation of CD4 T cells into TRM in order to develop vaccination and therapeutic protocols that harness the unique properties of these cells to prevent and fight site-specific infections." (PMID 25071787, 2014). "Indeed, one such study utilized antibodies to deplete CD4+ T cells and showed that previous infection with C. trachomatis does not induce strong protective immunity upon secondary infection, and that CD4+ T cells are not essential for clearance of infection." (PMID 25386180, 2014). "Therefore, it is intriguing to speculate whether this expansion of the CD161–TCRVα7.2+CD4– T cell subset might be an effect of CD161 down-regulation on former CD161+ MAIT cells, taking place during early stages of infection." (PMID 25369333, 2014). "In group 3 patients controlling the infection in the presence of CD8+ T-cells only, it is possible that low levels of CD4+ were already present in the blood or other CD4+ T-cells residing in lymphoid organs may have played a role in protection in the first period after transplantation." (PMID 25166270, 2014). "In vaccinated animals, soon before the onset of infection occurred 15-16 weeks post-vaccination, the recalled PCV2-specific immune response was characterized by moderate PCV2-specific IFN-γ secreting cell frequencies and augmented productivity together with reactive CD4+CD8+ memory T cells." (PMID 24735253, 2014). "The involvement of CD28 in the modulation of protective immunity against T. cruzi was shown by mediating the activation of both CD4+ and CD8+ T cells, the production of IFN-γ, and, as a consequence, the production of NO efficient to control parasite growth during the acute phase of the infection." (PMID 25197170, 2014). "To confirm that the dynamics observed with HIV-infected cells were independent of infection-mediated changes in target cell physiology, we carried out similar imaging analysis utilizing CD4+ targets pulsed with low nanomolar concentrations of synthetic HIV peptides." (PMID 24551068, 2014). "Furthermore, this interaction resulted in effective chlamydial antigen presentation to infection-sensitized but not naïve CD4+ T cells, as indicated by enhanced T cell proliferation and secretion of Th1-type cytokines." (PMID 25551828, 2014). "Although signaling by IFNγ is crucial for control of Mtb, clinical data shows that IFNγ present at the site of ongoing infection is inadequate to clear bacteria and IFNγ levels produced by CD4+ T cells do not correlate with disease progression or protection provided by BCG vaccination." (PMID 24391492, 2014). "The reduced frequency of infected GC B cells in SAP-deficient mice may be due to the inability to proliferate in the absence of robust CD4 help, or may be a product of the reduced frequency of GC B cells available for infection in these mice." (PMID 24789087, 2014). "The rise in glucocorticoid levels during infection is related to the extensive apoptosis of immature CD4+CD8+ cells, which accounts for the atrophy of the thymus, together with the premature release of recent thymic emigrant cells, including CD4+CD8+ thymocytes." (PMID 25330249, 2014). "CD4+ T-cells were infected with 3000 infectious units of B- and C-HIV R5 viruses, and 1250 infectious units of B- and C-HIV R5X4 and X4 viruses, which we determined here (data not shown) and previously to be virus inoculums that ensure infections within the linear range." (PMID 25387392, 2014). "Furthermore, this interaction resulted in effective chlamydial antigen presentation to infection-sensitized but not naïve CD4+ T cells and enhancement of protective immunity." (PMID 25551828, 2014). "In fact, we show that infection by an Env-independent virus is not inhibited by CD4+ exosomes." (PMID 25423108, 2014).